PRKDC (protein kinase, DNA-activated, catalytic subunit)
Description:
Serine/threonine-protein kinase that acts as a molecular sensor for DNA damage. Involved in DNA non-homologous end joining (NHEJ) required for double-strand break (DSB) repair and V(D)J recombination. Must be bound to DNA to express its catalytic properties. Promotes processing of hairpin DNA structures in V(D)J recombination by activation of the hairpin endonuclease artemis (DCLRE1C). Recruited by XRCC5 and XRCC6 to DNA ends and is required to (1) protect and align broken ends of DNA, thereby preventing their degradation, (2) and sequester the DSB for repair by NHEJ. Acts as a scaffold protein to aid the localization of DNA repair proteins to the site of damage. The assembly of the DNA-PK complex at DNA ends is also required for the NHEJ ligation step. Found at the ends of chromosomes, suggesting a further role in the maintenance of telomeric stability and the prevention of chromosomal end fusion (By similarity). Also involved in modulation of transcription. As part of the DNA-PK complex, involved in the early steps of ribosome assembly by promoting the processing of precursor rRNA into mature 18S rRNA in the small-subunit processome. Binding to U3 small nucleolar RNA, recruits PRKDC and XRCC5/Ku86 to the small-subunit processome. Recognizes the substrate consensus sequence [ST]-Q. Phosphorylates 'Ser-139' of histone variant H2AX, thereby regulating DNA damage response mechanism. Can phosphorylate C1D not only in the presence of linear DNA but also in the presence of supercoiled DNA. Acts as a regulator of the phosphatidylinositol 3-kinase/protein kinase B signal transduction by mediating phosphorylation of 'Ser-473' of protein kinase B (PKB/AKT1, PKB/AKT2, PKB/AKT3), promoting their activation. Contributes to the determination of the circadian period length by antagonizing phosphorylation of CRY1 'Ser-588' and increasing CRY1 protein stability, most likely through an indirect mechanism (By similarity). Plays a role in the regulation of DNA virus-mediated innate immune response by assembling into the HDP-RNP complex, a complex that serves as a platform for IRF3 phosphorylation and subsequent innate immune response activation through the cGAS-STING pathway. Also regulates the cGAS-STING pathway by catalyzing phosphorylation of CGAS, thereby impairing CGAS oligomerization and activation. Also regulates the cGAS-STING pathway by mediating phosphorylation of PARP1.
Synonyms: DNA-PKcs; S473K; HYRC; HYRC1; DNPK1; p350; DNAPK; XRCC7; DNAPKc; DNA-PKC; p460; IMD26
Tractability: Small molecule: a drug acting on it is in phase 2 or 3 trials; a structure with a bound ligand is known; a high-quality ligand is known; it belongs to a druggable protein family. PROTAC: UniProt records ubiquitination sites on it; ubiquitination databases record sites on it; its protein half-life has been measured; a small molecule that binds it is known.
Target class: Enzyme; Atypical protein kinase group; Atypical protein kinase PIKK family; Protein Kinase; Kinase
Chemical probes: AZD-7648 (high quality), BAY-8400, Nedisertib (high quality)
Gene: Protein-coding gene on chromosome 8 (47,773,108 to 47,960,182, reverse strand). Ensembl gene ENSG00000253729.
Subcellular location: Nucleus; Nucleus, nucleolus; Cytoplasm, cytosol
Subcellular location (Human Protein Atlas): Nucleoplasm
Pathways (Reactome):
Immune System: Cytosolic sensors of pathogen-associated DNA; IRF3-mediated induction of type I IFN
DNA Repair: Nonhomologous End-Joining (NHEJ)
Metabolism of proteins: E3 ubiquitin ligases ubiquitinate target proteins
Gene Ontology:
Molecular function: DNA-dependent protein kinase activity; double-stranded DNA binding; histone H2AXS139 kinase activity; protein binding; protein domain specific binding; protein kinase activity; protein serine kinase activity; protein serine/threonine kinase activity; RNA binding; RNA polymerase II-specific DNA-binding transcription factor binding; U3 snoRNA binding; enzyme binding; kinase activity
Biological process: activation of innate immune response; cellular response to insulin stimulus; DNA damage response; double-strand break repair; maturation of 5.8S rRNA; mitotic G1 DNA damage checkpoint signaling; negative regulation of apoptotic process; negative regulation of cGAS/STING signaling pathway; peptidyl-serine phosphorylation; peptidyl-threonine phosphorylation; positive regulation of double-strand break repair via nonhomologous end joining; positive regulation of transcription by RNA polymerase II; protein phosphorylation; regulation of epithelial cell proliferation; regulation of smooth muscle cell proliferation; small-subunit processome assembly; telomere capping; double-strand break repair via alternative nonhomologous end joining; double-strand break repair via nonhomologous end joining; immunoglobulin V(D)J recombination; intrinsic apoptotic signaling pathway in response to DNA damage; negative regulation of protein phosphorylation; positive regulation of erythrocyte differentiation; positive regulation of lymphocyte differentiation; positive regulation of platelet formation; and 8 more
Cellular component: chromatin; chromosome, telomeric region; DNA-dependent protein kinase complex; DNA-dependent protein kinase-DNA ligase 4 complex; membrane; nonhomologous end joining complex; nucleolus; nucleoplasm; nucleus; protein-containing complex; protein-DNA complex; small-subunit processome; transcription regulator complex; cytosol
Genetic constraint (gnomAD): Loss-of-function variants: 56 observed, 382.87 expected, observed/expected ratio (o/e) 0.15, 90% interval 0.12 to 0.18. The upper end of that interval is the gene's LOEUF score, 0.18, which puts it in group 1 of 6, group 1 being the genes least tolerant of losing a copy. Missense variants: 4,121 observed, 4,576.8 expected, observed/expected ratio (o/e) 0.9, 90% interval 0.88 to 0.92. Synonymous variants: 1,766 observed, 1,701.9 expected, observed/expected ratio (o/e) 1.04, 90% interval 1 to 1.08.
Gene-disease validity (ClinGen):
ClinGen rates the evidence that PRKDC causes each of these diseases.
severe combined immunodeficiency due to DNA-PKcs deficiency (autosomal recessive): Definitive. Severe combined immunodeficiency (SCID) due to DNA-PKcs deficiency is an extremely rare type of SCID characterized by the classical signs of SCID (severe and recurrent infections, diarrhea, failure to thrive), absence of T and B lymphocytes, and cell sensitivity to ionizing radiation.
Homologues: Orthologues: chimpanzee PRKDC (99% identical), macaque PRKDC (98% identical), guinea pig PRKDC (81% identical), mouse Prkdc (79% identical), pig PRKDC (79% identical), rat Prkdc (79% identical), tropical clawed frog prkdc (62% identical), zebrafish prkdc (58% identical). Paralogues in human: ATR (13% identical), TRRAP (13% identical), ATM (12% identical), SMG1 (11% identical), MTOR (10% identical).
Diseases named in the same sentence as PRKDC in open-access papers:
PRKDC is named in the same sentence as 259 diseases in open-access papers, as found by Europe PMC text mining. Sharing a sentence is not in itself a finding about the gene and the disease. The quoted sentences say what the papers report.
breast carcinoma (94 papers, 2010 to 2025). "Some studies have shown that PRKDC expression is significantly higher in breast cancer tissue samples; high expression of PRKDC is also associated with a higher tumor grade, positive lymph node metastasis, and chemoresistance." (PMID 39376611, 2024). "Based on cBioportal analysis, we found that the overall survival time of breast cancer patients with one gene mutation in PRKDC, NOS2, ARG1, or IDO1 was significantly shorter compared with patients without the mutations." (PMID 36373232, 2023). "In contrast, low protein expression of PRKDC was associated with a higher tumor grade and mitotic index, as well as survival, in breast cancer." (PMID 35054819, 2022). "Since the fraction of mutated PRKDC tumors in breast cancer is very low (1%), our main findings reporting that low expression of DNA-PKcs correlates with good survival is driven by wild-type tumors." (PMID 34504086, 2021). "In support of our findings, mutations in PRKDC have been previously implicated in breast cancer initiation and progression." (PMID 34504086, 2021). "Aberrant expression/activation PRKDC has been reported to be associated with chemoresistance in a variety of tumors including glioma, oral squamous cell carcinoma, ovarian cancer and breast cancer due to its function in DNA damage repair." (PMID 32661323, 2020). "Besides, the overall survival time of breast cancer patients with at least one gene mutation in PRKDC, NOS2, ARG1, and IDO1 (1191 patients) was significantly shorter compared with patients without the mutations (4575 patients)." (PMID 36373232, 2023). "In the case of breast cancer, higher expression levels of PRKDC were significantly associated with shorter overall survival, higher tumor grade, and positive lymph node status in patients, while downregulation sensitized MCF-7 cell lines to chemotherapeutics in vitro and in xenograft models." (PMID 35054819, 2022). "Moreover, higher PRKDC mutation and expression were correlated with ER− breast cancer immune pathway functions." (PMID 34745960, 2021). "The highly expressed PRKDC could promote breast cancer cell growth and was associated with poor survival of the patients." (PMID 33194682, 2020). "This indicated that mutations in PRKDC, NOS2, ARG1, and IDO1 were correlated to lower overall survival in breast cancer patients." (PMID 36373232, 2023). "By using IF assays, we found that NTF4 upregulated the expression of PRKDC, and that NTF4 and PRKDC co-localized in breast cancer cells." (PMID 36632451, 2023). "The results from the CPTAC dataset confirmed that PRKDC total protein is highly expressed in breast cancer, ovarian cancer, colon cancer, UCEC, and LUAD compared with normal controls, but not clear cell RCC." (PMID 35801800, 2022). "In particular, homologs AKT1, AKT2, ERBB2, FGFR2, and PIK3CA in CGC play important roles in breast cancer progression, mediating breast cancer risk, corresponding to the driver candidates RPS6KA1, SGK1, PTK2, IGF1R, PIK3CB, and PRKDC predicted by DriverMP." (PMID 38091511, 2022). "Using the CPTAC dataset, we evaluated the PRKDC phosphorylation level in tumor tissues as well normal tissues in 6 kinds of cancers, including breast cancer, colon cancer, clear cell RCC, UCEC, LUAD, and ovarian cancer." (PMID 35801800, 2022). "Taken together, our results show that both DNA-PKcs protein and PRKDC transcript are biomarkers that help identify basal-like cases both within ER + and ER- breast cancers." (PMID 34504086, 2021). "It is proved that PRKDC expression is significantly increased in breast cancer tissue samples compared with NATs and is correlated with reduced overall and progression-free survival in high-grade glioma patients." (PMID 32596394, 2020). "A previous study has implicated that downregulation of PRKDC-sensitized MCF-7 cells to chemodrugs in vitro, which is a potential prognostic and predictive marker of response to adjuvant chemotherapy in breast cancer patients." (PMID 32596394, 2020).
breast carcinoma (continued). "Another study has linked high levels of DNA-dependent kinase catalytic subunit D (PRKDC) to chemoresistance in breast cancer patients treated with adjuvant chemotherapy." (PMID 31682620, 2019). "The strongest evidence of association with breast cancer risk in BRCA2 mutation carriers was observed for rs6982040, located at 8q11.21 in intron 74 of the PRKDC gene (p = 2.7 × 10−3)." (PMID 27796716, 2017). "Similarly, PRKDC upregulation has been reported to induce a G2/M transition in MCF-7 breast cancer cells and the inhibition of its protein product has been reported to induce a G2/M arrest in primary NSCLC cells." (PMID 39684302, 2024). "High expression of PRKDC is also a prognostic marker of poor survival in breast cancer patients." (PMID 39376611, 2024). "Likewise, HR−HER2-positive breast cancer showed more differentially mutated genes (ERBB2, PRKDC, PTEN and NEB) than HR−HER2-zero breast cancer (only SLX4) compared to HR−HER2-low breast cancer (3 vs 1)." (PMID 37264417, 2023). "For example, studies have demonstrated that suppressing CDK5 can impede cell motility and tumor development in the mesenchymal breast cancer cell lines MDA-MB-231 and BT549, while elevated expression of PRKDC promotes breast cancer cell proliferation by regulating p38 MAPK signaling." (PMID 38091511, 2022). "We reviewed the functional properties of the driver nodes found to have the highest impact in controlling the essential proteins; they are ERBB2, SRC, PDPK1, PRKDC, mTOR for breast cancer, ERBB2, AKT1, GSK3B, ABL1 in pancreatic cancer, and RET in ovarian cancer." (PMID 28871116, 2017). "Furthermore, PRKDC downregulates the sensitivity of the HR+/HER2-type breast cancer cells (MCF-7 line) to chemotherapeutic agents in vitro and in xenograft mouse models, indicating that PRKDC is a prognostic biomarker of chemoresistance in breast cancer patients." (PMID 39376611, 2024). "Using cBioPortal, it was found that PRKDC (DNA‐PK encoding gene) tended to coexist with the functional markers of MDSCs which include NOS2 (iNOS‐encoding gene), Arg1 (Arg1‐encoding gene), and IDO1 (IDO‐encoding gene) in 19 breast cancer studies involving 9134 patients/9555 samples." (PMID 36373232, 2023). "Secondly, NTF4 is a new regulator of breast cancer EMT and cancer progression, which targets PRKDC (DNA-PKcs) and ANXA1 and activate AKT and NF-κB pathways." (PMID 36632451, 2023). "AZD7648 and Afurestertub inhibited expression of PRKDC, AKT signaling, and the mesenchymal markers (N-cadherin and SNAIL), as well as breast cancer cell migration and invasion." (PMID 36632451, 2023). "Phosphorylation of GSK-3β (Ser9) was promoted by activated PRKDC/AKT signaling, while the expression of SNAIL was increased and E-cadherin was decreased in NTF4 over-expressing breast cancer cells." (PMID 36632451, 2023). "Nineteen genes from these gene sets were identified to be amplified and upregulated in breast cancer but only five of them NBN, PRKDC, RFWD2, UBE2T, and YWHAZ meet criteria in all breast cancer molecular subtypes." (PMID 33925616, 2021). "Thus, we focused on PRKDC and ANXA1 and found both proteins to be significantly increased in NTF4 stably expressing breast cancer cells, as well as constituents of an activated AKT signaling pathway." (PMID 36632451, 2023). "Moreover, inhibition of PRKDC/AKT signaling and ANXA1 effectively rescues NTF4-mediated breast cancer metastasis and invasion." (PMID 36632451, 2023). "(D) Box-plots of HR (BRCA1, BRCA2, ATR) and NHEJ (PRKDC, XRCC5, XRCC6) protein expression levels (ratio to pool) in the different groups of breast cancer cell lines according to AZD1775 response characteristics (recovering-basal, sensitive-basal and recovering-luminal)." (PMID 32628111, 2020).
glioblastoma (86 papers, 2008 to 2026). The most malignant astrocytic tumor (WHO grade IV). "In contrast, PRKDC mutations were less common in some other types of tumors such as thyroid cancer (0.99%), glioblastoma (1.37%), and liver cancer (1.61%)." (PMID 34702253, 2021). "For example, rs7003908 of PRKDC was reported to be associated with prostate and urinary bladder cancer in north-Indian populations and glioblastoma in United States." (PMID 23437280, 2013). "We examined the co‐expression of PRKDC and MB21D1 (encoding cGAS) in glioblastoma tissue samples from the CGGA transcriptomic database." (PMID 36574362, 2023). "For example, the expression of ATR and PRKDC are similarly elevated across diverse glioblastoma subtypes compared to normal brain and their expression is strongly correlated." (PMID 26486089, 2015). "In addition, analysis of PRKDC and MB21D1 expression in glioblastoma of grades II, III, and IV, indicates that PRKDC and MB21D1 expression increased significantly with the aggressiveness of the tumors." (PMID 36574362, 2023).
glioma (63 papers, 2005 to 2025). A benign or malignant brain and spinal cord tumor that arises from glial cells (astrocytes, oligodendrocytes, ependymal cells). "Variations in genes involved in DNA repair, cell cycle, metabolism, and inflammation pathways have been recognized as a key basis of inherited glioma susceptibility, such as PRKDC, XRCC1, PARP1, ERCC1, ERCC2, EGF, and IL13." (PMID 36733406, 2023). "Genetic variants of XRCC7(PRKDC)-6721G/T is located in the intron 8 of chromosome 8 and has shown to elevate the risk of glioma and renal cell carcinoma." (PMID 33685509, 2021). "Only one PRKDC polymorphism, intron 8 G6721T (SNP rs7003908), has been identified to be associated with a significant increase risk in carcinogenesis (glioma, bladder, colorectal, and prostate cancer)." (PMID 28684677, 2017). "We analyzed the associations of one IL-10 and one PRKDC single nucleotide polymorphism with patient clinical factors in 481 glioma patients using Cox proportional hazard models and Kaplan-Meier curves." (PMID 27811370, 2016). "We investigated associations between IL-10 and PRKDC gene polymorphisms and prognosis in low- and high-grade glioma patients." (PMID 27811370, 2016). "Although previous association studies linked IL-10 and PRKDC genetic polymorphisms with glioma risk, few focused on the effects of these alterations on glioma patient prognosis." (PMID 27811370, 2016). "In the present study, we selected one single nucleotide polymorphism (SNP) in IL-10 and one in PRKDC, each of which was reportedly associated with glioma risk." (PMID 27811370, 2016). "Interleukin-10 (IL-10) and DNA repair gene PRKDC mutations are implicated in the development of multiple human cancers, including glioma." (PMID 27811370, 2016). "IL-10 SNP rs1800871 was associated with improved survival in low-grade glioma cases, while PRKDC SNP rs7003908 was correlated with poor prognosis in high-grade patients." (PMID 27811370, 2016). "PRKDC gene polymorphisms are also correlated with glioma risk." (PMID 27811370, 2016). "Previous reports show that PRKDC is preferentially expressed in glioma stem cell-like populations and stabilizes Sox2, a core transcription factor that maintains the glioma stem cell niche in GBM." (PMID 41271669, 2025). "After WHO grade stratification, we found that rs1800871 in IL-10 correlated with increased OS in low-grade glioma cases, while rs7003908 in PRKDC correlated with poor prognosis in high-grade cases." (PMID 27811370, 2016). "This study was also the first to demonstrate that the PRKDC rs7003908 C/C genotype was correlated with poor prognosis in high-grade glioma patients." (PMID 27811370, 2016). "In the present study, we observed reduced OS and PFS in high-grade glioma patients carrying the PRKDC rs7003908 C/C genotype." (PMID 27811370, 2016). "These cells expressing LMNA, PRKDC, and PARP1 transcripts are molecularly more dedifferentiated glioma stem-like cells, specifically OPC-like cells." (PMID 41271669, 2025). "Our data align with this finding, indicating that PRKDC and LMNA expression in the glioma stem cell compartment contribute to TMZ resistance in GBM." (PMID 41271669, 2025). "Indeed, data mining confirms that, in gliomas at least, there is a strong correlation between ATR and PRKDC transcripts." (PMID 26486089, 2015).